PIK3CA (phosphatidylinositol-4,5-bisphosphate 3-kinase catalytic subunit alpha)
Diseases named in the same sentence as PIK3CA in open-access papers (continued):
Sharing a sentence is not in itself a finding about the gene and the disease.
cancer (continued). "In addition, the Pik3ca gain-of-function mutation accelerates cancer progression of PTEN-deficient prostate in mice." (PMID 31551414, 2019). "However, contradictory reports exist in the literature regarding the effect of PIK3CA gene mutations on the prognosis of different cancers." (PMID 31905960, 2019). "This contrasts with the prevailing view that PIK3CA mutations occur heterozygously in cancer." (PMID 30948643, 2019). "Activating missense mutations in PIK3CA p110α subunit has been proven in many cancers." (PMID 32099598, 2019). "For example, the involvement of p110α, which is encoded by PIK3CA, in human cancer has been hypothesized since 1995, and PIK3CA started to appear in later volumes of the journal." (PMID 31610621, 2019). "Prospective clinical studies are needed to determine whether differences in the allele dosage of activating PIK3CA mutations influence therapeutic outcomes in cancer." (PMID 30948643, 2019). "The discovery that PIK3CA mutations are involved in human cancers has resulted in the development of multiple genetically engineered mouse models that have allowed for the role of Pik3ca mutations in cancer development and progression to be studied in detail and in multiple types of cancer." (PMID 31018529, 2019). "Although PIK3CA-mutated cancer is usually sensitive to mTOR inhibition, activation of GSK3β in response to PI3K/mTOR inhibition may lead to the resistance to PI3K/mTOR inhibitors in PIK3CA-mutated cancer." (PMID 31277692, 2019). "This discrepancy may have occurred because patients in the present study had advanced cancer with increased treatment burden or because PIK3CA mutations are significantly more frequent in HR-positive cancers than in HR-negative cancers." (PMID 31088410, 2019). "PIK3CA is reported to be one of the most commonly mutated oncogenes in human cancer." (PMID 31443495, 2019). "PIK3CA helical domain mutations are present in numerous cancer patients; thus, it has been hypothesized that targeting SGK3 may be an effective treatment option for tumors harboring PIK3CA helical domain mutations." (PMID 30975125, 2019). "Therefore, loss of PTEN and/or mutations of PIK3CA result in constitutive activation of Akt/mTOR, which have been documented in various cancers." (PMID 31370278, 2019). "Importantly, the PIK3CA mutation most commonly detected in human cancers include OvCa patients’ specimens and OvCa cell lines is the H1047R mutation." (PMID 31284467, 2019). "Finally, mutations in the TERT promoter and NRAS, PTEN, and PIK3CA genes are occasional molecular drivers of cancer in the pediatric population." (PMID 31456750, 2019). "Further studies of induced pluripotent stem cells, animal models, and cancer cell lines on the role of somatic mosaic activating PIK3CA mutations in cell fate are warranted and could be of great importance for precision medicine in both cancer and PROS." (PMID 30919936, 2019). "Better understanding of context-dependent consequences of chronic PIK3CA activation could offer fundamental insights into the pathogenesis of PIK3CA-associated cancers." (PMID 30197175, 2018). "The phosphatidylinositol-4,5-bisphosphate 3-kinase, catalytic subunit alpha (PIK3CA) gene is mutated and/or amplified/gained in numerous cancers, leading to dysregulation of the PI3K-AKT-mTOR pathway and resulting in increased cell proliferation, angiogenesis and survival." (PMID 29902261, 2018). "Mutations in the PIK3CA gene, encoding the p110α catalytic subunit, have been reported in ~30% of breast cancers (mainly estrogen receptor positive; ER+), and many other cancer types (including ovarian, urological, neural and brain, lung, colorectal and pancreatic)." (PMID 29757235, 2018). "Indeed most macroscopic overgrowth in PROS occurs in mesodermal and neuroectodermal derivatives, while PIK3CA-associated cancers most commonly arise in ectodermal or endodermal epithelia." (PMID 30197175, 2018).
cancer (continued). "Mutations of PIK3CA (6–35%) are more frequent in cancers as compared to AKT1 mutations (0–8%)." (PMID 29549527, 2018). "However, due to the high abundance in different cancer entities, oncogenic mutated PIK3CA is an attractive target for cancer therapy." (PMID 30001368, 2018). "In vitro pharmacologic sensitivity screen among a broad panel of cancer cell lines revealed that sensitivity to alpelisib was positively associated with the presence of PIK3CA mutation, amplification or copy number gain, which was confirmed by an in vivo study using mouse models." (PMID 31093356, 2018). "However, the EGFR mutation was estimated to be present in all the cancer cells, whereas the PIK3CA mutation was estimated to be present in only 38% of the cancer cells." (PMID 29738578, 2018). "This analysis was performed to gain experimental evidences on the miRNA functional involvement in cancer mechanisms, where often the growth signals are constitutively activated by a host of mutations (e.g., PIK3CA mutation, HER2 amplification, CDKN2A deletion)." (PMID 29868122, 2018). "Furthermore, we assessed the role of PIK3CA mutations on patients’ overall survival in both groups affected by cancer (CM/ESCC and ESCC)." (PMID 30619505, 2018). "Activating mutations in the PIK3CA gene encoding the p110α catalytic subunit of class IA PI3K are frequently mutated in several cancer types, and mutations in the PIK3CD gene encoding the p110δ catalytic subunit have been identified in primary immunodeficiency patients." (PMID 29616047, 2018). "Additionally, an individual had the PIK3CA p.H1047L rs121913279 variant, which has been reported at high frequency in breast (n = 183), large intestine (n = 64) and endometrial (n = 43) cancers in COSMIC, ID = COSM776 and COSM94987." (PMID 29641532, 2018). "However, larger cohort studies using multiple cancer cell lines with PIK3CA mutations and animal models are needed to validate these findings before their application in a clinical setting." (PMID 28036259, 2017). "In addition, in vitro studies involving various cancer cell lines suggest that PIK3CA mutations are predictive markers of everolimus sensitivity." (PMID 29207615, 2017). "Some PIK3CA mutations result in minimal activation of AKT as compared to PTEN loss suggesting that AKT inhibitors may be more efficacious in cancers with AKT alterations and PTEN loss." (PMID 28420128, 2017). "In particular, SW48 and LIM1215 cancer cells, that are wild type (WT) for KRAS, BRAF, NRAS and PIK3CA genes, and GEO cancer cells, that have a KRAS codon 12 mutation, are sensitive to the anti-epidermal growth factor receptor (EGFR) monoclonal antibody cetuximab." (PMID 28978118, 2017). "Thus, we applied the Cancer Hallmark Network Framework to study the PIK3CA mutations in a human signaling network." (PMID 28392480, 2017).
cancer (continued). "A comprehensive analysis of the mutational landscape across 12 major cancer types revealed that PIK3CA mutations occurred in 35.5% of all breast cancer tumors, but luminal A subtype tumors had the highest frequency at 46.6% of all the samples harboring the mutation." (PMID 28392480, 2017). "Therapies that target mutant KRAS or PIK3CA proteins could also be investigated as prophylactic therapies in individuals with Noonan and Cowden syndromes, who have high cancer risk because they carry germline mutations in these genes." (PMID 28755461, 2017). "The human and canine PIK3CA genes share 99.8% sequence identity, and in 8 of our 9 PIK3CA mutant cases, the missense mutation affected amino acid 1047, the same position most commonly mutated in human cancers." (PMID 29190660, 2017). "Therefore, the mutation of PIK3CA should be determined as a biomarker to administer deguelin for better clinical outcomes in cancer patients." (PMID 28134774, 2017). "Along the same lines, PIK3CA activating mutations are widespread in cancer." (PMID 28532501, 2017). "As PIK3CA is an oncogenic driver gene, A3A- and/or A3B-mediated somatic mutations may contribute to HPV-associated cancer progression through mutations in PIK3CA." (PMID 28825669, 2017). "In cancer, activating PIK3CA mutations are frequent while PIK3CB is mutated less often." (PMID 28002804, 2017). "Our results suggest that PIK3CA mutations interact with other mutated proteins and may play a role in cancer progression or metastasis." (PMID 28392480, 2017). "Alterations resulting in PTEN loss and PIK3CA amplification, which are also targets for mTOR/P13K inhibitors, have been implicated in 7% and 9% respectively, in carcinomas of unknown primary." (PMID 28302097, 2017). "Because cancer cell lines likely bear multiple mutations that could confound interpretation of results, it was important to determine the effects of PIK3CA-E545K mutation in an otherwise isogenic background." (PMID 27489350, 2016). "For example, PIK3CA mutations predicted to disable interfaces with regulator N-terminal SH2 domains (above) have a statistical significant cross-cancer lower survival and higher hazard ratio (Cox, p = 1.3e−2) than those predicted to affect the C-terminal SH2 domains." (PMID 27698488, 2016). "By comparisons of doubling time and MDR between the mutant and wild-type NCI-60 cell lines, we revealed that mutations of APC, KRAS, and PIK3CA might correlate with enhanced malignancy of cancer cells." (PMID 26937901, 2016). "PIK3CA mutations in several types of human cancer have been associated with patient prognosis." (PMID 27388016, 2016). "Most somatic PIK3CA mutations in human cancers occur within two hot spots: E545K and H1047R." (PMID 27317099, 2016). "Four patients harbored hotspot PIK3CA mutations most commonly seen in cancer." (PMID 27631024, 2016). "However, the contribution of the PIK3CA mutation to the biology of these cancers has been under-investigated and the population of patients most likely to benefit from these agents has yet to be determined." (PMID 26863299, 2016). "In this study, the reference signature for oncogenic, active PI3K-dependent pathways had been derived by using isogenic KI human mammary epithelial cells expressing the PIK3CA(E545K) or PIK3CA(H1057R) cancer alleles, that are suitable for generating bona-fide oncogene specific signatures." (PMID 27542212, 2016). "Somatic mutations in the PIK3CA gene are frequently found in a variety of human cancers." (PMID 26909613, 2016). "However, there exists limited data on mutant PIK3CA associated with prognostic value for stage II or III cancers." (PMID 27074743, 2016).
cancer (continued). "ARID1A mutation in cancer tended to occur in a synergistic fashion with PIK3CA." (PMID 27323812, 2016). "The PI3K/AKT/mTOR signaling pathway is the most frequently activated signaling network in cancer and recurring mutations in this network have been identified, including mutations (PIK3CA, AKT, and PTEN), amplifications (PIK3CA, PIK3CB and AKT) and deletions (PTEN, INPP4B)." (PMID 26989080, 2016). "In particular, PIK3CA is one of the most mutated genes in many types of cancers." (PMID 26860319, 2016). "On the other hand, as stronger MDR implies severer drug resistance of cancer cell lines, the mutation of PIK3CA may confer stronger drug resistance." (PMID 26937901, 2016). "To determine if similar tumors could be initiated in the setting of a hotspot mutation in PIK3CA commonly encountered in human cancers, we developed the Fc+Pik3caH1047R murine model." (PMID 26863299, 2016). "The PIK3CA E545K mutation has been identified in numerous cancers." (PMID 27317099, 2016). "From these evidences, we could make hypothesis that cancer-specific high expression of PIK3R1 increases activation of PIK3CA and as a result, negatively regulated apoptotic function cause cancer in breast." (PMID 27490120, 2016). "Our study suggests that targeting glutamine metabolism may provide a specific form of therapy for cancer patients harbouring PIK3CA mutations." (PMID 27321283, 2016). "Furthermore, we now show that the concomitant inhibition of mTOR and MEK promotes the apoptotic demise of HNSCC cells specifically in tumors expressing the PIK3CA oncogene, the most frequently driver mutation in this cancer type." (PMID 26882569, 2016). "PIK3CA mutation represents a clinical subset of diverse carcinomas." (PMID 27554588, 2016). "Some studies demonstrated that PIK3CA mutations were associated with risk of cancers." (PMID 25834816, 2015). "Overall, the results from these studies suggest that not only the presence of PIK3CA mutation, but also the specific type of cancer, may be important considerations in successfully targeting this mutation." (PMID 26469692, 2015). "Moreover, inhibition by ARQ 092 and ARQ 751 was more prevalent in cancer cell lines containing PIK3CA/PIK3R1 mutations compared to those with wt-PIK3CA/PIK3R1 or PTEN mutations." (PMID 26469692, 2015). "As PIK3CA-mutated patients were not significantly older than the comparing group (mean 68.0 years [SD, 8.0] vs 65.7 years [SD, 10.5 years], p=0.176), we performed a multivariable logistic regression analysis with age and PIK3CA mutation regarding the occurrence of additional cancer within the past." (PMID 25473901, 2015). "PIK3CA, the gene encoding the p110α isoform is frequently mutated in various human cancers." (PMID 26655726, 2015). "On the basis of the clinical spectrum of this patient (see results), after the positive testing for PIK3CA mutation, this patient would be classified as PROS B. It is worth noting that the PIK3CA c.3140 A>G [p.H1047R] change is the most common cancer-associated PIK3CA mutation." (PMID 25915946, 2015). "Moreover, PIK3CA is a well-known oncogene, the activation of which has been implicated in various cancers." (PMID 25654238, 2015). "In our study, we demonstrated that using the BEAMing technology, testing for 21 oncogenic mutations in BRAF, EGFR, KRAS and PIK3CA genes in the plasma cfDNA of patients with advanced cancers referred for treatment with experimental targeted therapies, is feasible." (PMID 25980577, 2015). "However, in another study with a panel of human cancer cell lines derived from various tissues, the sensitivity was found to correlate with both PIK3CA and PTEN loss." (PMID 26469692, 2015). "Furthermore, we analyzed the mutation status of a panel of cancer-related genes: only PIK3CA mutations were exclusively observed in regorafenib resistant mCRC tumors with low TTC." (PMID 26317543, 2015). "Activating mutations of PIK3CA p110α are among the most frequent alterations in human cancers." (PMID 25096023, 2014).
cancer (continued). "PIK3CA, another gene often mutated in various types of cancer, may also hold a role in the alteration of the phosphatidylinositol 3 kinase (PI3K)/Akt pathway in EC." (PMID 24526917, 2014). "Using high-sensitive detection methods, even very low percentage of the cancer cells carrying PIK3CA mutation could be identified." (PMID 25054828, 2014). "The PIK3CA gene is one of the most frequently mutated oncogenes in human cancers." (PMID 25340423, 2014). "However for the patients with the age <59 years or with family cancer history, PIK3CA mutations were correlated with worse overall survival (log rank P = 0.039, 0.026 respectively)." (PMID 25054828, 2014). "However in the ESCC patients with family cancer history, PIK3CA mutations were independently correlated with worse overall survival (multivariate hazard ratio (HR) = 10.493, 95% CI: 2.432–45.267, P = 0.002)." (PMID 25054828, 2014). "Given the morphologic diversity of early neoplasias, their differences in association with both concurrent and future cancer, and the recently described genetic differences in 1q gain and PIK3CA mutation frequencies, we were struck by the similarity of their transcriptional profiles." (PMID 24887547, 2014). "Gain of function mutations in the PIK3CA (phosphatidylinositol-4,5-bisphosphate 3-kinase, catalytic subunit alpha) gene is found in 25–40% of cancers, with alterations mainly clustering in two hotspots within the helical (exon 9) and catalytic (exon 20) domains." (PMID 25214840, 2014). "PI3K p110 catalytic subunit (PIK3CA) mutations may be driver mutations in certain cancers responsible for metastasis." (PMID 24931005, 2014). "PIK3CA mutations represent one of the most common molecular aberrations inbreast cancer." (PMID 25192370, 2014). "PIK3CA mutations represent one of the most common genetic aberrations inbreast cancer." (PMID 25192370, 2014). "A number of studies reported that the phosphoinositide-3-kinase-catalytic-alpha (PIK3CA) gene is frequently mutated in the helical domain within exon 9 (codons 542 and 545) and in the kinase domain within exon 20 (codon 1047) of several types of human cancer." (PMID 25220666, 2014). "The underlying mechanism is most probably the heterogeneous PIK3CA mutation in cancer cells." (PMID 25054828, 2014). "Somatic missense mutations in PIK3CA are found in approximately 15% of all human cancers." (PMID 25488803, 2014). "Together, our results indicate that targeting XIAP or the proteasome in CRC with PIK3CA mutations may offer a promising strategy to exploit the therapeutic potential of TRAIL in cancer therapy." (PMID 25501831, 2014). "PIK3CA mutations were observed more frequently in ER+ cancers compared to TNBC (19 vs. 8%)." (PMID 25051360, 2014). "In addition to gain-of-function mutations, PIK3CA is activated through gene amplifications in several cancers." (PMID 25343854, 2014). "PIK3CA is the most frequently mutated oncogene in human cancers." (PMID 23768168, 2013). "Likewise, loss of MGMT expression, another characteristic of PIK3CA-mutated carcinomas, has been reported to be more frequent in tumors with mucinous differentiation compared with tumors without mucinous differentiation." (PMID 23785428, 2013). "In conclusion, we have found that PIK3CA mutations lead to a shift towards a highly glycolytic phenotype, and that despite suggestions that cancer cells are adept at utilising alternative nutrient sources, PIK3CA mutant cells are not able to compensate for glucose withdrawal." (PMID 23028762, 2012). "In addition to somatic mutations, genomic amplification of PIK3CA has also been reported in several human cancers." (PMID 22666248, 2012).